RNU2-2 (RNA, U2 small nuclear 2)
Synonyms: U2; DEE119; RNU2-2P; RNU2B
Gene: Small nuclear RNA gene on chromosome 11 (62,841,619 to 62,841,809, reverse strand). Ensembl gene ENSG00000222328.
Gene-disease validity (ClinGen):
ClinGen rates the evidence that RNU2-2 causes each of these diseases.
developmental and epileptic encephalopathy 119 (autosomal dominant): Strong. A developmental and epileptic encephalopathy caused by the variants in the RNU2-2 gene, in which most reported variants are de novo.
Homologues: Orthologues: chimpanzee U2 (97% identical), mouse Gm23444 (97% identical), mouse Gm23472 (97% identical), mouse Gm23849 (97% identical), mouse Gm23971 (97% identical), mouse Gm24950 (97% identical), mouse Rnu2-10 (97% identical), rat U2 (97% identical), mouse Gm24497 (96% identical), rat U2 (96% identical), mouse Gm25813 (96% identical), mouse Gm25939 (96% identical), and 4 more. Paralogues in human: U2 (96% identical), U2 (93% identical), RNU2-4P (90% identical), RNU2-3P (89% identical), RNU2-52P (87% identical), RNU2-6P (86% identical), RNU2-17P (86% identical), RNU2-36P (86% identical), RNU2-59P (86% identical), RNU2-48P (85% identical), RNU2-14P (85% identical), RNU2-26P (84% identical), and 66 more.
Diseases named in the same sentence as RNU2-2 in open-access papers:
RNU2-2 is named in the same sentence as 4 diseases in open-access papers, as found by Europe PMC text mining. Sharing a sentence is not in itself a finding about the gene and the disease. The quoted sentences say what the papers report.
ReNU syndrome (1 paper, 2026). "De novo variants in snRNA genes RNU4-2 (ReNU syndrome), RNU5B-1 and RNU2-2 have been linked to dominant neurodevelopmental disorders (NDDs), revealing a large unexpected contribution of noncoding RNA genes to genetic diseases." (PMID 41912934, 2026).
neurodevelopmental disorder (2 papers, 2025 to 2026). A behavioral and cognitive disorder with onset during the developmental period that involves impaired or aberrant development of intellectual, motor, or social functions. "Using this insight, we report neurodevelopmental disorders (NDDs) caused by rare variants in two major spliceosomal RNA encoding genes, RNU2-2 and RNU5B-1." (PMID 40442284, 2025).
RNU2-2 also shares sentences with these, for which no sentence is quoted: epileptic encephalopathies (1 paper); genetic diseases (1).